ALB (albumin)
Diseases named in the same sentence as ALB in open-access papers (continued):
Sharing a sentence is not in itself a finding about the gene and the disease.
pulmonary hypertension (37 papers, 2012 to 2026). Increased pressure within the pulmonary circulation due to lung or heart disorder. "Additional markers such as elevated platelet counts, nucleated red blood cells, and low albumin levels suggest that both inflammation and hypercoagulability further compound the risk of pulmonary hypertension." (PMID 40827192, 2025). "The MLR and CRP/albumin ratio were associated with development of pulmonary arterial hypertension (p = 0.036, p = 0.006), and the lymphocyte/HDL ratio was associated with newly developed interstitial lung disease (p = 0.004)." (PMID 41464713, 2025). "Among all laboratory parameters, serum calcium and albumin were found to be significantly associated with the severity of pulmonary hypertension (p < 0.05)." (PMID 38558648, 2024). "Low albumin was associated with preserved LV EF, smaller dimensions of the left ventricle, reduced RV systolic function, severe tricuspid regurgitation, and pulmonary hypertension." (PMID 30637771, 2019). "The serum total protein and albumin level were significantly lower in pulmonary hypertension group (P < 0.05), which was associated with the ability of hepatic synthetic proteins and water sodium retention." (PMID 29921927, 2018). "Low albumin was also associated with right HF, tricuspid regurgitation, and pulmonary hypertension." (PMID 30637771, 2019). "Other reported risk factors for PGD, such as age, BMI, cardiac index, pulmonary hypertension, preoperative oxygen requirements, use of vasoactive medications, and donor characteristics may have confounded or overshadowed the potential benefits of albumin." (PMID 41227239, 2025). "Low albumin was associated with increasing age, higher urea and C‐reactive protein, lower sodium, hemoglobin, iron, less treatment with angiotensin‐converting enzyme inhibitor or angiotensin receptor blocker, reduced right ventricular function, and pulmonary hypertension." (PMID 30637771, 2019). "Perfusion studies were performed in supine position using either with full dose 148–185 MBq (4–5 mCi) of 99mTc-macroaggregated albumin (MAA) or half dose 74–93 MBq (2–2.5 mCi) for pregnant or pulmonary hypertension patients." (PMID 40746337, 2025). "A thorough binary analysis revealed a significant correlation between an SARC-F score of ≥4 and variables such as age, pulmonary arterial hypertension, albumin levels, and C-reactive protein in patients with SSc." (PMID 40095540, 2025). "Previous research has demonstrated that the serum albumin concentration serves as an independent prognostic indicator for patients with pulmonary hypertension." (PMID 38580915, 2024). "68Ga-labeled mannosylated human serum albumin (68Ga-NOTA-MSA) has also shown promising results for PET imaging of sentinel lymph nodes and assessment of pulmonary arterial hypertension-induced inflammation in lungs." (PMID 38532026, 2024). "This relationship between CRP and pulmonary hypertension was supported by the results of another study, which also evaluated haptoglobin, albumin and PON-1, and confirmed the relationship between pulmonary hypertension and acute phase response, especially in the positive APP CRP and haptoglobin." (PMID 29143665, 2017).
rectal cancer (37 papers, 2010 to 2025). A primary or metastatic malignant neoplasm that affects the rectum. "A series of studies have reported associations of low-level serum albumin or low-level total protein with postoperative AL in rectal cancer." (PMID 32461995, 2020). "Another study of patients undergoing rectal resection for rectal cancer observed an association of high Δ albumin with an eventful postoperative course." (PMID 30422980, 2018). "The current study shows a significant association between a low preoperative serum albumin of less than 35 g/ L, with a reduction in overall survival for patients undergoing surgery for rectal cancer." (PMID 23590192, 2013). "Albumin–carcinoembryonic antigen ratio is a simple and effective clinical tool for predicting the recurrence and survival of patients with rectal cancer and is a useful supplement to the TNM stage." (PMID 39897534, 2024). "The SYST group had more ECOG greater than 2 patients (38% vs. 22%), more rectal carcinomas, more extrahepatic disease, lower albumin levels and higher alkaline phosphatase levels." (PMID 38935125, 2024). "Another RCT found that ω-3 FAs capsules significantly reduced the Glasgow Prognostic Score (GPS), a prognostic cancer marker based on inflammation composed of CRP and albumin, in patients with local advanced rectal cancer receiving neoadjuvant radiotherapy." (PMID 37686570, 2023). "The novel albumin-related nutrition biomarker “LA”, which was defined as lymphocyte × albumin, was firstly introduced in rectal cancer patients." (PMID 37836576, 2023). "Only one study has investigated a combination of lymphocyte and albumin level values as a prognostic biomarker in patients with rectal carcinoma." (PMID 37750127, 2023). "In conclusion, we found that “lymphocyte × albumin (LA)”, the product of the lymphocyte count multiplied by the albumin concentration was a novel prognostic biomarker for stage II/III rectal cancer patients." (PMID 33658561, 2021). "Here, we explored the prognostic value of changes in pre- and post- neoadjuvant chemoradiotherapy (NCRT) plasma fibrinogen and serum albumin (FA) scores in patients with locally advanced rectal cancer (LARC)." (PMID 31814824, 2019). "Overall survival following surgery for rectal cancer became significantly poor in patients having preoperative serum albumin less than 35 g/L compared with those with a serum albumin greater than 35 g/L (P = 0.02)." (PMID 23590192, 2013). "Albumin can be used as a cost effective and a sensitive marker to predict survival in rectal cancer compared to other available inflammatory markers." (PMID 23590192, 2013). "Our aim was to evaluate if pre-operative serum albumin would predict survival after resection for rectal cancer." (PMID 23590192, 2013). "The aim of this study was to study the effect of preoperative serum albumin on survival following surgery for rectal cancer." (PMID 23590192, 2013). "Therefore, the assessment of ΔAlb is strongly advised for stratifying patients with higher risk of developing postoperative complications, especially for the rectal cancer patients with normal preoperative albumin levels." (PMID 40432957, 2025). "Multivariate logistic regression analysis revealed four independent risk factors for surgical site infection: low albumin level, rectal cancer, blood loss, and lack of perioperative oral care." (PMID 37204529, 2023). "Therefore the evidence is accumulating to suggest a survival effect of the SIR in rectal cancer which can be predicted with easily accessed parameters such as albumin and white cell count." (PMID 23590192, 2013). "On the other hand, ischaemia modified albumin has been proved as an effective predictor of anastomosis leakage, which could be useful in the early detection of this most serious periperative complication common amongst rectal cancer patients." (PMID 26788017, 2015).
rectal cancer (continued). "This study aimed to determine the value of albumin–carcinoembryonic antigen ratio (ACR) in predicting the progression-free survival (PFS) and overall survival (OS) of patients with rectal cancer." (PMID 39897534, 2024). "Alarmingly, there was an important increase in the diagnoses of advanced stages of rectal cancer and a notable increase in case complexity, as evidenced by elevated ASA scores and altered albumin levels across the years under study." (PMID 38131987, 2023). "Another study found that patients with stage IV colon and rectal cancer with a CEA level greater than or equal to 275 ng/mL and an albumin level less than 2.7 g/dL had a significantly shorter survival time." (PMID 21176210, 2010). "The present study demonstrated that ∆ALB had significantly predictive value for postoperative outcomes in rectal cancer patients with normal preoperative albumin levels, but not for the patients with hypoproteinemia." (PMID 40432957, 2025).
viral hepatitis (37 papers, 2008 to 2026). An acute or chronic inflammation of the liver parenchyma caused by viruses. "Viral hepatitis, intravenous hormone usage, low platelet count, and low albumin level were significant factors associated with UGIB." (PMID 35879668, 2022). "Several risk scores, including liver stiffness values, age, sex, albumin and, for viral hepatitis, HBV-DNA, have been proposed and used in clinical practice." (PMID 36294318, 2022). "The aMAP score involved age, sex, albumin-bilirubin and platelets, and satisfactorily predicted the risk of HCC development among over 17,000 patients with viral and non-viral hepatitis from 11 global prospective studies." (PMID 37525116, 2023). "In conclusion, we have identified four independent risk factors of UGIB after renal transplantation, including intravenous hormone usage, low platelet count, low albumin level and viral hepatitis." (PMID 35879668, 2022). "Increase in bilirubin level during viral hepatitis is related to liver cell damage and the degree of hepatic necrotizing inflammation, while reduction in ALB level is also related to the severity of liver synthetic function damage." (PMID 35646962, 2022). "Our results showed that, in NAFLD and viral hepatitis patients, even before their albumin levels, total bilirubin, and prothrombin time became abnormal, their IMAT value decreased significantly comparing to the healthy volunteers (P < 0.001)." (PMID 28101103, 2016). "Platelet count, nonlinear albumin, and hemoglobin were associated with VB in patients with viral hepatitis." (PMID 40591542, 2025). "The two groups were similar in terms of sex, age, ECOG‐PS score, Child–Pugh grade, albumin‐bilirubin (ALBI) score, modified ALBI grade, BCLC stage C, AFP level, viral hepatitis, PVTT type, number of tumors, hepatic vein invasion, and extrahepatic metastasis." (PMID 36951443, 2023). "LCMV-WE also induced viral hepatitis as determined by increased Alanine Aminotransferase (ALT) and Aspartate Aminotransferase (AST) levels and decreased albumin levels in guinea pigs that met endpoint criteria (EC)." (PMID 33573250, 2021). "More patients with alcoholic cirrhosis had viral hepatitis, but subjects with AAH exhibited increased MELD scores, AST levels and WBC counts with decreased hemoglobin and albumin." (PMID 25461442, 2014). "Platelet count, nonlinear albumin, INR, and total bilirubin were associated with HE in patients with viral hepatitis." (PMID 40591542, 2025). "The currently conventional biochemical markers for liver function, such as bilirubin, albumin, and liver enzymatic assays, often do not exhibit detectable changes at early stage of viral hepatitis." (PMID 28101103, 2016). "Characteristics including age, BMD, body mass index (BMI), creatinine (Cr), AST, albumin, high-sensitive C-reactive protein (hsCRP), thyroid stimulating hormone (TSH), history of proteinuria and alcoholic consumption had significant difference across these viral hepatitis groups." (PMID 30911051, 2019).
Hypokalemia (36 papers, 2009 to 2026). An abnormally decreased potassium concentration in the blood. "The multivariate logistic analysis showed that the white blood cell count, serum albumin level, direct bilirubin, and operation time were risk factors for hypokalemia after radical EC resection (p < 0.05)." (PMID 39840263, 2024). "The multivariate logistic analysis showed that the white blood cell count, serum albumin level, direct bilirubin, and operation time were independent risk factors for hypokalemia in patients after radical EC resection (p < 0.05)." (PMID 39840263, 2024). "Higher scores reflected greater risk: elevated white blood cell count, low serum albumin, high direct bilirubin, and prolonged operation time all increased the likelihood of hypokalemia." (PMID 39840263, 2024). "The ultrafiltration volume at the peritoneal equilibration test and the blood albumin level were found to be independent risk variables for hypokalemia by multivariate stepwise linear regression analysis." (PMID 38021540, 2023). "The prediction model for hypokalemia risk with individualized scores based on the patient's white blood cell count, serum albumin level, direct bilirubin, and operation time can screen out high-risk patients who might develop hypokalemia." (PMID 39840263, 2024). "Herein, the differences in various indicators were analyzed between the two groups according to whether hypokalemia occurred in EC patients after the operation, and white blood cell count, serum albumin level, direct bilirubin, and operation time were risk factors." (PMID 39840263, 2024). "The prediction model for hypokalemia risk using individualized scores on the patient's white blood cell count, serum albumin level, direct bilirubin, and operation time can screen out high-risk patients who might develop hypokalemia, which is beneficial to clinical practice." (PMID 39840263, 2024). "Moreover, the operation time and preoperative albumin were found to be independent risk factors for postoperative albumin supplementation, whereas the body mass index (BMI) and preoperative hypokalemia were risk factors for postoperative potassium supplementation." (PMID 35689221, 2022). "Specifically, the high-persistent group exhibited a higher PIM3 score, lower albumin levels, higher serum lactate levels, a greater likelihood of mechanical ventilation usage, vasoactive drug usage, and hypokalemia compared to the other groups." (PMID 39044193, 2024). "First, individuals with hypokalemia tend to have poorer nutritional status, higher levels of inflammatory markers, and lower albumin concentrations." (PMID 39634334, 2024). "The findings of our study revealed notable variations in age distribution, principal pathology types, PIM3 score, mechanical ventilation, vasoactive drug usage, hypokalemia, albumin levels, and lactate levels among the different groups." (PMID 39044193, 2024). "This group with a stable low AGI grading was characterized by lower levels of PIM3 score, serum albumin and lactate, as well as a lower incidence of mechanical ventilation, utilization of vasoactive drug, and hypokalemia upon admission to the PICU." (PMID 39044193, 2024). "The group with serum albumin <3.9 g/dl or serum potassium <4.0 mmol/l before yokukansan administration had a shorter time of hypokalemia onset than the group with serum albumin ≥3.9 g/dl (P = 0.008) or serum potassium ≥4.0 mmol/l (P = 0.019)." (PMID 38868417, 2023). "The group with low albumin (<3.9 g/dl) developed hypokalemia earlier than that of the group with high albumin (≥3.9 g/dl)." (PMID 38868417, 2023). "These included 8.1%, 9.9% and 3.4% patients with low hemoglobin, low albumin and hypokalemia, respectively." (PMID 35689221, 2022). "The multiple linear regression model showed that the binge–purge type (p = 0.02), lower caloric intake (p = 0.03), and a lower serum albumin level (p = 0.04) predicted a lower nadir hypokalemia during refeeding." (PMID 34362446, 2021).
Hypokalemia (continued). "The study revealed that patient’s serum albumin levels (≥2.82 mg/dl) at the start of L-AMB administration and history of hypokalemia prior to L-AMB administration were independent risk factors significantly contributing to the occurrence of hypokalemia." (PMID 24669255, 2014). "Biochemical studies showed hypokalaemia (K+ 2.81 mmol/L) and hypoproteinaemia (albumin 33.7 g/L)." (PMID 37525276, 2023). "Biochemical studies showed hypokalaemia (K+ 3.32 mmol/L) and hypoproteinaemia (albumin 26.6 g/L)." (PMID 37525276, 2023). "Although hypomagnesemia is known to cause refractory hypokalemia, our study found the negative correlation of albumin-corrected magnesium level and serum potassium level." (PMID 34362446, 2021). "When data from only patients with the restrictive type were considered (sub-analysis 3), the model (p = 0.02, F = 2.7) showed that lower caloric intake (p = 0.04) predicted a lower nadir potassium level, with albumin having a tendency to affect nadir hypokalemia (p = 0.08)." (PMID 34362446, 2021). "In the analysis of postoperative blood test indicators, the total protein, albumin, and calcium ions in patients with postoperative hypokalemia were lower than those without hypokalemia." (PMID 39840263, 2024). "Correcting metabolic acidosis in hemodialysis patients improved serum albumin and nPCR without hypokalemia or significant interdialytic weight gain." (PMID 37545875, 2023).
Jaundice (36 papers, 2014 to 2025). Yellow pigmentation of the skin due to bilirubin, which in turn is the result of increased bilirubin concentration in the bloodstream. "Not to forget the relative contraindication of TMP/SMX in children less than 2 months of age as it displaces indirect bilirubin from albumin, increasing the risk of jaundice and subsequent kernicterus highlighted in multiple studies." (PMID 41221142, 2025). "After 49 days of hospitalization, the patient’s liver function normalized (total bilirubin within normal range, albumin increased from 31.3 to 35.1 g/L), coagulation function (PT) returned to normal, and jaundice resolved." (PMID 40922328, 2025). "Knudsen postulated that the cephalocaudal progression of jaundice arises from conformational alterations within bilirubin-albumin complexes." (PMID 38054187, 2023). "As for transaminase (AST and ALT) and albumin, patients with total bilirubin levels above 2.0 mg/dL (n = 268) were excluded from the analysis to minimize the influence of obstructive jaundice due to PC." (PMID 36765521, 2023). "Therefore, we also detected the frequency of elevated UCB and albumin in jaundice patients to be almost similar." (PMID 39669649, 2024). "A potential weakness of the ALBI score is that it could be influenced by albumin replacement therapy or the presence of obstructive jaundice when in some cases HCC may present with obstructive jaundice, and thus might not accurately reflect true liver functional reserve at all times." (PMID 29339752, 2018). "Patients with invasive IPMN often develop jaundice and cholangitis, and as a result, the PNI value as well as serum albumin level might be decreased in these patients." (PMID 33436649, 2021). "Strikingly low level of albumin (<35g/L) (86.8%), increased levels of aspartate aminotransferase (AST) (84.2%) and alanine aminotransferase (ALT) (63.2%) and jaundice (total bilirubin (T-BIL)>17.1μmol/L, direct bilirubin (D-BIL)>6.8 μmol/L) (76.3%) were common." (PMID 27483437, 2016). "Interestingly, we noted that Singapore Asian patients commonly presented with jaundice, and had significant higher levels of bilirubin, a higher MELD score, and lower levels of albumin at diagnosis." (PMID 27101826, 2016).